CXCL17 (C-X-C motif chemokine ligand 17)
Diseases named in the same sentence as CXCL17 in open-access papers (continued):
Sharing a sentence is not in itself a finding about the gene and the disease.
psoriasis (2 papers, 2022 to 2024). An autoimmune condition characterized by red, well-delineated plaques with silvery scales that are usually on the extensor surfaces and scalp. "IL17, IL-23, CXCL16 and CXCL17 was also significantly decreased by laboratory tests, suggesting that guselkumab has a good efficacy in the psoriasis treatment." (PMID 35693833, 2022). "With the development of the pathogenesis of psoriasis, the role of IL-17, IL-23, CXCL16, CXCL17 and tumor necrosis factor-α (TNF-α) in the immunoinflammatory process of psoriasis is becoming clear." (PMID 35693833, 2022).
pulmonary TB (2 papers, 2021). "Serum CXCL17 levels were also analyzed in two additional comparative cohorts of coronavirus disease 2019 (COVID-19) and pulmonary tuberculosis (TB) patients." (PMID 33717172, 2021). "In M. tuberculosis–infected individuals, serum levels of CXCL17 are higher among latent TB-infected (LTBI) subjects than individuals with active pulmonary TB (PTB), suggesting a protective role." (PMID 34561226, 2021). "In humans, lower serum CXCL17 levels are observed among active pulmonary TB patients when compared with subjects with latent TB infection and healthy controls, suggesting a protective role." (PMID 34561226, 2021). "However, CXCL17 may have a dispensable role during pulmonary TB." (PMID 34561226, 2021).
tuberculosis (2 papers, 2021). A chronic, recurrent infection caused by the bacterium Mycobacterium tuberculosis. "The expression of the CXCL17 gene was also found upregulated in group 3 innate lymphoid cells isolated from lung tissues of patients with tuberculosis (TB), suggesting a role for CXCL17 against Mycobacterium tuberculosis (Mtb) infection." (PMID 33717172, 2021). "In the current study, we addressed whether CXCL17 participates in immune protection against TB in a model of hypervirulent M. tuberculosis HN878 infection in mice." (PMID 34561226, 2021). "Importantly, the role of CXCL17 in TB immunity should be further addressed in murine models of infection with different M. tuberculosis strains and in larger cohorts of TB patients as well." (PMID 34561226, 2021). "However, the administration of exogenous CXCL17 to WT mice and the absence of CXCL17 signaling in knockout animals do not alter the susceptibility to TB in the murine model of hypervirulent M. tuberculosis HN878 infection." (PMID 34561226, 2021).
viral infection (2 papers, 2021 to 2024). "Hence, next we investigated if CXCL17, along with other clinical characteristics, could have certain diagnostic value to discriminate between both viral infections." (PMID 33717172, 2021). "In viral infections, there is only a report suggesting that CXCL17 participates in immunity against genitourinary herpes infections." (PMID 33717172, 2021).
acute respiratory distress syndrome (1 paper, 2021). Progressive and life-threatening pulmonary distress in the absence of an underlying pulmonary condition, usually following major trauma or surgery. "Here, we report high levels of CXCL17 in serum from patients with acute respiratory distress syndrome (ARDS) associated with pandemic influenza A(H1N1)." (PMID 33717172, 2021).
Aden (1 paper, 2021). "Thus, high expression of CXCL16 and CXCL17 may also contribute to the formation of an immune suppressive tumor microenvironment in patients with Aden." (PMID 34459571, 2021).
atherosclerosis (1 paper, 2019). A disease characterized by the build-up of fatty material and calcium deposition in the arterial wall resulting in partial or complete occlusion of the arterial lumen. "Atherosclerosis and chemokines are strongly related, but the role of the chemokine CXCL17 in atherogenesis is still poorly understood." (PMID 31934638, 2019). "Therefore, the aim of this study is to investigate the relationship between CXCL17 and atherosclerosis-related diseases." (PMID 31934638, 2019). "However, little is known about the biological function of CXCL17 in atherosclerosis which is one of the chemokine of CXC family." (PMID 31934638, 2019). "However, the function of CXCL17 in the development of cardiovascular diseases, especially in atherosclerosis, is unclear." (PMID 31934638, 2019).
autoimmune disorders (1 paper, 2021). "Our data indicate that the production of CXCL17 is also highly potentiated during the early stages of pandemic influenza A(H1N1), as the serum levels reported here are as high as those found in other inflammatory and human autoimmune disorders." (PMID 33717172, 2021).
breast tumors (1 paper, 2012). "Previous reports showed that CXCL17 was expressed in normal stomach, trachea, and lungs (bronchiolar epithelium and a subset of alveolar lining cells), although some colon and breast tumors were CXCL17-positive." (PMID 22952881, 2012).
colorectal tumor (1 paper, 2019). "Additional studies on primary colorectal tumor showed that the expression of CXCL17 on tumor cells promotes angiogenesis and tumor infiltration of immune cells." (PMID 31620367, 2019).
depression (1 paper, 2025). "However, we found evidence of causal effects of genetic liability to depression on levels of CXCL17 (p = 1.7*10−07), and PRSS8 (p = 6.6*10−06)." (PMID 40281223, 2025).
diffuse large B-cell lymphoma (1 paper, 2024). "CXCL17 is also involved in the pathogenesis of diffuse large B-cell lymphoma, where it serves as a prognostic marker." (PMID 39451532, 2024).
endometrial cancer (1 paper, 2024). Primary or metastatic malignant neoplasm involving the endometrium (mucous membrane that lines the endometrial cavity). "Colorectal, breast, hepatocellular, and type I endometrial cancer all showed significantly lower levels of CXCL17 mRNA or protein compared to type I endometrial cancer and pancreatic intraductal papillary mucinous carcinoma." (PMID 38384293, 2024).
experimental autoimmune encephalomyelitis (1 paper, 2023). An autoimmune demyelinating disease of the central nervous system that is produced experimentally in animals by the injection of homogenized brain or spinal cord in Freund's adjuvant. "A lack of such inhibition may explain, in part, the perturbed trafficking of lymphoid and myeloid cells and exacerbated disease reported in CXCL17-deficient mice utilized in a model of experimental autoimmune encephalomyelitis (EAE)." (PMID 37942327, 2023).
gastric diseases (1 paper, 2022). "Our results suggested that CXCL17 expression was gradually upregulated during the pathological progress of gastric diseases (NAG-NOR < AG-IM < GC-IM), but significantly downregulated when GC occurred." (PMID 36614059, 2022).
glioblastoma (1 paper, 2024). The most malignant astrocytic tumor (WHO grade IV). "The high expression of CXCL17 was also linked with glioblastoma prognosis." (PMID 38384293, 2024).
Hepatitis (1 paper, 2014). Inflammation of the liver. "The CXCL17 expression was also been examined on human hepatitis tissues (n = 8) with mean (± SEM) density of 29.05±11.13." (PMID 25303284, 2014). "In the present study, we found abundant CXCL17+ cell infiltrated in HCC tumor but were relatively rare in hepatitis liver." (PMID 25303284, 2014).
ischemia (1 paper, 2025). A hypoperfusion of the BLOOD through an organ or tissue caused by a PATHOLOGIC CONSTRICTION or obstruction of its BLOOD VESSELS, or an absence of BLOOD CIRCULATION. "Although the classification of CXCL17 as a GPR35 ligand remains controversial, recent studies demonstrate that the CXCL17-GPR35 axis mediates myeloid-derived suppressor cell recruitment during liver ischemia-reperfusion injury and activates IL-17 signaling to promote chemoresistance in CRC." (PMID 41459506, 2025).
lymph node metastasis (1 paper, 2026). "Our results revealed CXCL17 expression was significantly correlated with lymph node metastasis and clinical stage (P < .05)." (PMID 41496085, 2026).
oral squamous cell carcinoma (1 paper, 2026). "However, the expression profile and functional characterization of CXCL17 in oral squamous cell carcinoma (OSCC) remain inadequately explored." (PMID 42255223, 2026).
pulmonary diseases (1 paper, 2023). "Therefore, CXCL17 might attenuate DEE-induced lung damage by recruiting and activating pulmonary macrophages, which is expected to be a novel therapeutic target for DEE-associated lung diseases." (PMID 37624152, 2023). "In addition, CXCL17 may serve as a new therapeutic target gene for DEE-related pulmonary diseases." (PMID 37624152, 2023).
respiratory infections (1 paper, 2021). "For instance, it has been shown that CXCL17 has a potent bactericidal activity over bacteria causative of respiratory infections." (PMID 33717172, 2021). "Past studies have provided indirect evidence about a possible role of CXCL17 in immunity against respiratory infections." (PMID 33717172, 2021). "In this context, our study represents the first direct evaluation of the expression of CXCL17 during respiratory infections in humans." (PMID 33717172, 2021). "However, despite CXCL17 being one of the most highly expressed chemokines in the human lung, its potential role in human respiratory infections has not been studied." (PMID 33717172, 2021).
skin tumor (1 paper, 2021). "Our study showed that CXCL17 expression was decreased in the skin tumor of CCL17 TG mice, while IL-4 expression was increased." (PMID 33670758, 2021). "CXCL17, CCR2, and CCL5 mRNA levels were significantly decreased in skin tumors of CCL17 TG mice compared with WT mice." (PMID 33670758, 2021).
stable angina (1 paper, 2019). "The logistic regression analysis showed that CXCL17 was an independent risk factor for unstable angina." (PMID 31934638, 2019). "In our study, CXCL17 was found to be an independent risk factor for unstable angina." (PMID 31934638, 2019). "Logistic regression analyses of association between serum CXCL17 levels and unstable angina." (PMID 31934638, 2019). "We observed that the unstable angina group had higher CXCL17 levels compared with the stable angina and the control group." (PMID 31934638, 2019).
tumor (49 papers, 2012 to 2026). "We revealed that higher CXCL17 in tumor center was associated with reduced postoperative neutrophil, preoperative monocyte and postoperative leukocyte." (PMID 42255223, 2026). "Another ligand, CXCL17, plays a central role in various malignancies, associated with tumor development, invasion and metastasis." (PMID 41459506, 2025). "A review by Shabaana revealed that CXCL17 is highly expressed in various tumor tissues and is closely associated with tumor cell proliferation, apoptosis resistance, angiogenesis, and metastasis." (PMID 37666495, 2024). "Precise mechanistic studies have shown that CXCL17 is associated with increased intratumoral infiltration of MDSCs, TAMs, and Tregs that mediate tumor immunosuppression, while decreasing CD4+ and CD8+ T cells with antitumor properties." (PMID 37666495, 2024). "CXCL17 has been associated with immune suppression and recruitment of tumor‐associated macrophages (TAMs)." (PMID 39711402, 2024). "The CXCL17 gene codes for a homeostatic, mucosa-associated chemokine involved in innate immunity that accelerates tumor angiogenesis and progression." (PMID 27511445, 2016). "To evaluate the correlation between CXCL17 expression and tumor development, we also analyzed the association between CXCL17 expression and the clinicopathological parameters." (PMID 25303284, 2014). "In comparison with the use of CXCL17-unresponding cells (from the upper chamber of the chemotaxis assay), CXCL17-recruited cells caused a striking enhancement in tumor formation of CXCL17-SW620 cells." (PMID 22952881, 2012). "Moreover, a high CXCL17 expression and a higher rate of tumor-infiltrating CXCL17-expressing cells have been found to be associated with unfavorable prognosis in HCC patients." (PMID 33499054, 2021). "In malignant intraductal papillary mucinous carcinoma, CXCL17 is downregulated and is associated with decreased DC infiltration, implying that it might be one strategy for tumor escape from immune surveillance." (PMID 25303284, 2014). "Thus, CCL17 attenuates tumor immunity by increasing Tregs and Th2 cells, while it decreases MDSCs through reductions in CXCL17, which may work as a “safety-net” to reduce the risk of malignant tumors in the Th2-dominant environment." (PMID 33670758, 2021). "Our results showed that CXCL17 expression was mainly expressed in cytoplasm of tumor cells apart from detecting in leukocytes of tumor stroma." (PMID 41496085, 2026). "CXCL17 was stained strongly in the infiltration of inflammatory cells and fibroblasts in the surrounding stroma of tumor." (PMID 41496085, 2026). "Elevated CXCL17 expression was correlated with advanced tumor stage, increased distant metastasis, and significantly shorter overall survival." (PMID 42255223, 2026). "Based on our previous proteomics studies of OSCC patients, we reported the elevated CXCL17 expression in tumor tissues compared to adjacent non-tumor tissues." (PMID 42255223, 2026). "Multivariate analysis confirmed tumor cell-derived CXCL17 as an independent prognostic factor for overall survival." (PMID 42255223, 2026). "This tumor-promoting role is further supported by CXCL17’s ability to inhibit autophagy and activate the LKB1-AMPK signaling pathway while modulating immune cell infiltration." (PMID 41459506, 2025). "The bacterium downregulates MUC1 and CXCL17 expression, which contributes to the reversal of the immunosuppressive tumor microenvironment (TME), leading to OSCC growth inhibition." (PMID 37666495, 2024). "CXCL17 is also involved in the intratumoral infiltration of MDSCs and TAMs and thus mediates immunosuppression in tumor tissues." (PMID 37666495, 2024). "Our findings are in line with earlier studies that demonstrate CXCL17 has a function in tumor development and progression and is overexpressed in a number of cancer types." (PMID 38384293, 2024).
tumor (continued). "The heatmap constructed based on the results of transcriptome sequencing of tumor tissues demonstrated that P. gingivalis treatment reduced the expression of pro‐tumorigenic chemokines such as CXCL17, which plays a role in the recruitment of MDSCs and TAMs." (PMID 37666495, 2024). "Even though numerous studies have demonstrated that CXCL17 is highly expressed in primary tumor samples and cancer cell lines, other studies have demonstrated that this cytokine is underexpressed in cancers." (PMID 38384293, 2024). "Another study on the role of CXCL17 in the lung metastasis of the breast tumor cells provides additional evidence to substantiate the chemokine facilitation of tumor dissemination." (PMID 36905477, 2023). "As a new member of the CXC family, CXCL17 is abundantly expressed in the mucosa of the respiratory and gastrointestinal tracts, and it functions in chemotaxis, immune homeostasis, and tumor immune response." (PMID 37624152, 2023). "CXCL17 induces accumulation of the CD11b+Gr-1+ myeloid-derived suppressor cells (MDSCs) in the lungs and promote tumor angiogenesis and extravasation of cancer cells to the lungs through the overexpression of PDGF-BB." (PMID 36905477, 2023). "This is a high number compared to the ectopically expressed chemokines CXCL16 and CXCL17 that were previously shown to stain 5 and 17% of the tumor cells in primary CC tumors." (PMID 38156105, 2023). "Subcluster 5, distinctly derived from the tumour tissue, overexpressed mucus secretion‐related genes (CXCL17, TFF3, MUC5AC, SPINK4 and MSMB, etc.)." (PMID 35075805, 2022). "The explanation for the observed improvement is most likely that GPR55 is a marker for T cells and B cells in lymph nodes, whereas CEA, CXCL16 and CXCL17, are markers for tumor cells of epithelial origin." (PMID 35562947, 2022). "Our data showed that both culture supernatant and cell lysate of TCh3 tumor cells contained a higher level of CXCL17 and CXCL16 than those of TAb2 tumor cells, in line with our RNA-seq data." (PMID 35366939, 2022). "We found that low CXCL17 expression more frequently appeared in cases with deeper tumor invasion (p = 0.015) and larger tumor diameter (p = 0.003)." (PMID 36614059, 2022). "Further studies using other cell types would be necessary to elucidate the role of CXCL17 in tumor immunity in the skin." (PMID 33670758, 2021). "In the present experiments, we showed that increased production of IL-4 induced a decrease in CXCL17, leading to suppression of tumor formation by blocking the recruitment of MDSCs into the tumor microenvironment." (PMID 33670758, 2021). "The prognostic value of CXCL17 mRNA was even more pronounced when the analysis was restricted to tumor cells expressing low CEA mRNA levels." (PMID 35008827, 2021). "At the same time, CCL17 attenuates MDSCs via a pathway including IL-4 and CXCL17, downregulating tumor formation." (PMID 33670758, 2021). "In conclusion, we have shown that CCL17 attenuates tumor immunity by increasing the levels of Tregs and Th2 cells, while it decreases MDSCs through CXCL17 reductions." (PMID 33670758, 2021). "In contrary, expression of CXCL17 by tumor cells was shown to recruit CD11b+Gr1highF4/80− immune cells and to promote tumor progression in mice." (PMID 31620367, 2019). "A number of studies indicate that CXCL17 can directly recruit immunosuppressive cells, such as neutrophils, macrophages, and MDSCs, to inflammatory sites and tumor tissues." (PMID 30755260, 2019). "Consistently, there were fewer metastatic foci and decreased tumor sizes in the lungs of anti-Gr-1 antibody treated, when compared with isotype treated, CXCL17 pre-treated mice." (PMID 30755260, 2019). "Consistently, more tumor nodules and increased size of tumors were found in the lungs of CXCL17 pre-treated mice compared with those of control mice." (PMID 30755260, 2019).